RELA (RELA proto-oncogene, NF-kB subunit)
Diseases named in the same sentence as RELA in open-access papers (continued):
Sharing a sentence is not in itself a finding about the gene and the disease.
cancer (continued). "Based on our results and those of previous findings, RELA is associated with poor survival in several cancers and may be a key oncogene for tumorigenesis and development." (PMID 33194633, 2020). "Moreover, antisense non-coding RNA at the INK4 locus (ANRIL) is upregulated in adult T-cell leukemia and associates with EZH2 and the RelA/p65 subunit of NFκB, which enhances NFκB signaling and promotes cancer cell proliferation." (PMID 33050576, 2020). "We first tested our hypothesis by inducing skipping of the 105 base pair (bp)-long exon 7 of RELA, a critical component of the NF-κB pathway implicated in inflammation and multiple types of cancer." (PMID 30107853, 2018). "Our group previously showed that IKKε controls cancer-associated RelA Ser536 phosphorylation." (PMID 30223576, 2018). "As IL-1β has also been linked to the expression of other cancer-associated cytokines, we tested the impact of miR-7-5p or si-RelA on expression of IL-6 and IL-8, and found that both miR-7-5p and si-RelA reduced the levels of secreted and intracellular IL-6 and IL-8." (PMID 27203220, 2016). "Given the effect of the RelA T505A mutation, it might be expected that this site or region of the RelA transactivation domain would be also mutated in human cancer or that SNPs in this region would predispose to liver or other diseases." (PMID 26853469, 2016). "Other tumors expressed low levels of RelA, but maintained a prominent fraction of cells with nuclear RelA (nPcL); these cancers may harbor mutations in NF-kB pathway genes." (PMID 26460486, 2015). "Furthermore, NF-κB/RelA is implicated in many hallmarks of cancer, including proliferation, prevention of apoptosis, and promotion of angiogenesis and metastasis." (PMID 26172294, 2015). "Our results indicate that overexpression of hTREX84 is associated with cancer cell transformation, proliferation and may be regulated by RelA/p65." (PMID 22952718, 2012). "Moreover, the increased cell expansion was associated with enhanced expression of nuclear NF-κB (RelA/p65), a protein complex that controls the transcription of genes including those responsible for cancer cell survival and proliferation." (PMID 20975993, 2010). "Significantly, phosphorylation of the p65/RelA subunit at Ser‐276 was elevated in patient samples of colorectal cancer harboring oncogenic mutations of the K‐Ras gene, and the expression levels of NF‐κB target genes were drastically enhanced in several cancer tissues." (PMID 31580526, 2019). "RelA, also known as p65, is the prototypical member of NF-κB that is persistently activated in lung and many other cancers." (PMID 40948895, 2025). "Lu and Yarbrough reported that RELA phosphorylation contributes to cancer progression through regulating NF-κB signaling." (PMID 40612864, 2025). "The augmented expression of TGFBR2, CDC25A, SMAD7, and RELA and downregulation of p27 are major events in cell proliferation and cancer invasion." (PMID 40761498, 2025). "The transcription factor RELA is a key player in the NF‐κB pathway, where it has a significant impact by increasing the expression of molecules that promote inflammation and cancer." (PMID 39821576, 2025). "Given the association of FOSL1 with elevated ERK1/2 activity and cancer cell invasion, we conducted gain-of-function assays with phosphomimetic mutants of FOSL1 and RELA." (PMID 40634284, 2025). "The increased expression of TGFBR2, CDC25A, SMAD7, and RELA and downregulation of p27 are major events in cell proliferation and cancer invasion." (PMID 40755497, 2025). "Our results indicated that higher gene expression levels of RELA were positively correlated with increased IC50 values of cancer therapy drugs, while UBA2, TRIM28, TRIM27, and CAPN3 showed opposite correlations." (PMID 38407971, 2024). "Studies have shown that TNF-α can trigger the movement of RelA into the nucleus, which in turn promotes the spread of cancer cells and aids their transition into a more aggressive form." (PMID 39834817, 2024).
cancer (continued). "It has been demonstrated that EZH2 interacts with the NF-κB transcription factors, RelA and RelB, to activate pro-inflammatory genes in several cancer types, suggesting that the NF-κB target gene signature is positively regulated by EZH2." (PMID 39204206, 2024). "Brd4, an I-BET target, is known to co-activate NF-κB signaling by interacting with acetylated RelA (p65) to promote its stability and transactivation activity in cancer cells." (PMID 38994961, 2024). "NanoPDLIM2 not only repressed the constitutive activation of RelA in cancer cells but also prevented the strong induction of RelA activation and MDR1 expression by the chemotherapy." (PMID 39718207, 2024). "It seems that the phosphorylation of RelA can also contribute to glycolysis and promote cancer progression alongside glucose transporter 1 (GLUT1)." (PMID 39834817, 2024). "The novel findings show for the first time that gold nanoparticles can inhibit interleukin-6 mRNA/protein secretion by upregulating miR-26a-5p and deactivating the RelA and NF-κBp50 transcription pathways in cancer cells." (PMID 38338683, 2024). "Specifically, in cancer cells, RELA and STAT3 physically interact, thereby integrating the NF-κB and JAK/STAT signaling pathways." (PMID 39435663, 2024). "Depletion of HSP60 leads to decreased Phosphorylating and transcriptional functioning of RelA (Belonging to the NF-κB family), elevation of E-cadherin protein, and consequent suppression of tumorigenesis in cancer cells." (PMID 39224812, 2024). "At this point, MYCN, ALK, RET and Phox2B built a complex network involved in different types of cancer, mostly involving the nervous system, also in regard to NF-κB (RelA/p65)." (PMID 38666930, 2024). "The NF-κB family, crucial for immune responses, inflammation, and cancer, includes five protomers: p50/NF-κB1, p52/NF-κB2, RelA/p65, cRel, and RelB." (PMID 39483891, 2024). "The analysis showed that TWIST1, RUNX1, CEBPA, and RELA were upregulated in carcinoma samples compared with normal renal tissues, whereas HIF1A was downregulated." (PMID 38724670, 2024). "It has been established that NF-κB p65 (RelA) stimulates the development of an inflammatory milieu that is conducive to the establishment of cancer." (PMID 37892820, 2023). "In summary, our findings suggest that H. pylori infection accelerates early‐stage GC progression by upregulating NFKB1/RELA transcription mediated by PIEZO1 in cancer cells." (PMID 37983931, 2023). "Quantitative analysis further affirmed the activation of NFKB1 and RELA in IM and cancer cells, signifying their up‐regulation as a pivotal early event in the process of GC progression." (PMID 37983931, 2023). "Our studies define kinetically distinct cascades of gene expression regulated by specific NF-κB subunits in BCR-activated B cells and thereby provide insights into exclusive functions of RelA and Rel in immunity and cancer." (PMID 37524800, 2023). "Previous studies have shown that the AKT/GSK3β/c-Fos/NFATc1, IGF-1/AKT/NF-κB (RelA) or TGF-β/Smad3/4 signaling cascade play a key regulatory role in BMM of many cancers." (PMID 37337244, 2023). "Our prior results demonstrated that the key components of the canonical NF‐κB signaling pathway, NFKB1 and RELA, were significantly upregulated at the protein level in GC and played a crucial role in the transition from inflammation to cancer." (PMID 37983931, 2023). "By rigorously identifying the target genes of each NF-κB subunit, these studies provide insights into exclusive functions of Rel and RelA in immunity and cancer." (PMID 37524800, 2023). "FKBP4 potentiates NF-kB pathway and transcriptional activity through IKKβ and enhances phosphorylation of IKKα/β, IkB and RelA (p65) in carcinoma." (PMID 36933095, 2023). "RELA, an important enhancer driver, is a subunit of NF-Kappa-B that acts as a proto-oncogene in many cancers including PTC." (PMID 36121916, 2022).
cancer (continued). "Previous studies demonstrated that RELA phosphorylation involved in the progression of various diseases including inflammatory disease and cancer by regulating NF-κB signaling and RELA also played a key role in mediating oncogene-induced aging." (PMID 35127830, 2022). "PTPN11 was a cancer-related gene that induced macrophages to differentiate into type M1 via activation of RELA signalling, which promoted inflammatory response as well as induced carcinogenesis." (PMID 36382627, 2022). "Kir2.2 can act as a constitutive activator to increase the phosphorylation of RelA, resulting in enhanced NF-kB activity and cell proliferation in cancer." (PMID 36100894, 2022). "The Nuclear Factor κB (NF-κB) family of transcription factors, comprising RelA/p65, RelB, c-Rel, p50/p105 (NF-κB1) and p52/p100 (NF-κB2), are important regulators of cancer cell biology." (PMID 36240066, 2022). "Previously published screens used conventional methods such as NF-κB reporter genes assays to test various chemical libraries in cancer cells or DNA strand exchange fluorescence resonance energy transfer to identify p65/RelA-specific inhibitors." (PMID 36093378, 2022). "Related to these findings, PAK4 is known to activate canonical NF-κB signalling (essentially via RELA, NF-κB p65 subunit) in cultured cancer cells, which contribute to cell proliferation and cell migration." (PMID 35920284, 2022). "Translating these observations on cancer, RelA-mediated metabolic rewiring can induce morphological characteristics typical of cancer cells, such as high proliferative rate and anchorage-independent growth." (PMID 35620053, 2022). "In early stage cancer cells, T505 phosphorylated RelA will contribute towards DNA repair, thus preventing the genomic instability leading to further cancer-causing mutations." (PMID 36240065, 2022). "Several in vitro studies reported that targeting redox activity of Ref-1 by APX3330 blocks activation of inflammatory modulators, such as RelA, IL-8 in human cancer lines." (PMID 35402225, 2022). "have shown that RELA has a potential role in the occurrence and development of cancer by regulating the expression of genes related to cell proliferation, migration, invasion, angiogenesis, and drug resistance to radiation or chemotherapy." (PMID 35166167, 2022). "Multiple cancer phenotypes were significantly enriched for conserved, pan-cell type, and top-ranked pre-TNFα RELA peak categories." (PMID 33495464, 2021). "RELA is a part of the nuclear factor Kappa-B family (NF-κB), which is concerned with inflammation and occurrence and progression of cancer." (PMID 34194527, 2021). "RELA is one of the transcription factors mediated inflammatory response and involved in cancer development." (PMID 33506873, 2021). "Since NF-κB directs pathways linking cancer with inflammation, we analyzed expression of transactivating NF-κB subunits c-Rel, RelB, and RelA in CSC-like cells." (PMID 33925297, 2021). "RELA has been shown to play a key role in mediating cancer-induced senescence in precancerous lesions." (PMID 33767987, 2021). "RELA activation has been found to be correlated with cancer development, suggesting the potential of RELA as a cancer biomarker." (PMID 34249899, 2021). "For cancer pathways, we assessed the activity of pathways associated with critical regulators of cancer function, such as PTEN, RELA (NF-kB pathway), etc., using gene expression signatures." (PMID 32575865, 2020). "The most comprehensively characterized transcription factor is nuclear factor-κB (NF-κB), which is regulated by BRD4 via binding to the acetylated lysine-310 residue of its RelA subunit in cancer cells." (PMID 33574760, 2020). "NF-κB affects cancer invasion and migration; hence, RelA of the NF-κB subunit was selected as the molecular target for metastasis for testing this new system." (PMID 31952106, 2020).
cancer (continued). "In this study, we focused on RelA as a target molecule for inhibiting cancer metastasis because it is a subunit of NF-κB that was recently reported to be involved in cancer metastasis, especially migration and invasion." (PMID 31952106, 2020). "Gold nanoparticles can target the Tf receptors on PCa cells to deliver siRNA to PCa cells, resulting in an inhibition of RelA (up to 35%) and a diminution in the growth and survival of cancer cells." (PMID 32784981, 2020). "RELA phosphorylation is involved in multiple inflammatory diseases and cancer progression by regulating NF-κB signaling." (PMID 32508531, 2020). "Nuclear phospho-Stat3 prolongs RelA nuclear localization via increasing its acetylation in various cancer cell lines." (PMID 31277415, 2019). "In the present study, we established that of the NF-κB subunits, only RelA together with its inhibitor IκBα, are consistently found inside the mitochondria of unstimulated cancer cells." (PMID 31484794, 2019). "RelA is reported to be overexpressed in several cancers including colon and patients with high RelA expression exhibit poor prognosis." (PMID 31351496, 2019). "RELA phosphorylation is involved in disease progression, notably inflammatory diseases and cancer, by regulating NF-κB signaling." (PMID 32117786, 2019). "Coincident with the molecular cloning of NF-κB/RelA and identification of its kinship to the v-Rel oncogene, it was anticipated that NF-κB itself would be involved in cancer development." (PMID 31779159, 2019). "Understanding the molecular mechanism that regulates RelA function will pave way for elucidating the role NF-κB subunits play in human inflammatory diseases and cancer, and bear a strong impact on the use of future NF-κB based cancer therapies." (PMID 31351496, 2019). "Constitutive canonical NF-κB signaling defined by an increased RelA nuclear localization or DNA binding activity is present in both cancer cell and histology specimens of human PDAC patients." (PMID 31277415, 2019). "Staining intensities of β-catenin, TCF4 and RelA (measured by H-score) followed similar trends in both normal and carcinoma samples." (PMID 31351496, 2019). "Another master regulator of cancer initiation and progression is NF-κB, a family of five transcription factors, NF-κB1/p105, NF-κB2/p100, RelA/p65, RelB and c-Rel, which can stimulate cell proliferation, angiogenesis, tumor metastasis and metabolism." (PMID 29351204, 2018). "Targeting the BRD4/acetylated RELA axis should be of value in NFκB-dependent cancers, such as lymphoma, where aberrant NFκB signaling is frequent, including through genetic mechanisms." (PMID 29415456, 2018). "A study found that the positive expression rate of the RELA in the tissue of HCC is significantly higher than that of liver tissue adjacent to carcinoma, suggesting that the RELA is closely related to the occurrence of HCC." (PMID 30671125, 2018). "With respect to HDAC6, it is also able to inhibit cancer cell migration by removing RelA acetylation." (PMID 29038521, 2017). "AEG-1 binds to RelA and promotes its nuclear translocation, positively regulates IL-8 expression and cancer progression." (PMID 28350359, 2017). "NF-κB/RELA p65 activation has been found to be correlated with cancer development, suggesting the potential of RELA as a cancer biomarker." (PMID 28212278, 2017). "In cancer cells, RelA can regulate mito-chondrial function via binding to mitochondrial DNA and repressing gene expression affecting oxidative phospho-rylation and ATP levels." (PMID 28768896, 2017). "Identification of the pathways responsible for nucleolar translocation of RelA would allow development of small molecules that act specifically on cancer cells by targeting chromatin bound RelA to nucleoli." (PMID 28718829, 2017). "PRL-3 induced phosphorylation of RelA, which promoted expression of HIF-1α and its transcriptional target miR-210, which was associated with increased invasiveness of cancer cells." (PMID 28350359, 2017).
cancer (continued). "The nuclear factor-kappa B (NF-κB) family, which includes NF-κB1/p105/p50, NF-κB2/p100/p52, RelA/p65, RelB, and cRel, has been widely studied in the field of immunology and cancer biology." (PMID 27391066, 2016). "Many cancer cell types show high levels of constitutive activity of NF-κB transcription factors (p50, p52, RelA/p65, c-Rel/REL and RelB)." (PMID 25915462, 2015). "Most members of the NF-κB family of proteins, which consists of RelA/p65, NF-κB1/p50, c-Rel, RelB, and NF-κB2/p52 (p52 NF-κB subunit), have been shown to be aberrantly activated in prosate cancer cells and tissues." (PMID 26622945, 2015). "This is a result of the concerted expression of genes related to cancer stem cell maintenance through NF-κB/RELA and STAT3 as downstream mediators of TLR9 signaling." (PMID 26046794, 2015). "Although RELB, which causes cancer progression, significantly induced CCID formation the major role in this process was attributed to RELA/NFKB1 (“canonical” pathway)." (PMID 26513020, 2015). "Phosphorylation of Ser536 of RelA has been shown to be important for RelA nuclear import and activity, as well as cancer cell proliferation." (PMID 25510503, 2015). "Specifically, TNFα stimulation or overexpression of RelA is sufficient to promote EMT of carcinoma cells." (PMID 26678048, 2015). "NF-κB is a transcriptional factor of the Rel family proteins, including p65 (RelA), RelB, c-Rel, p50 (NF-κB1) and p52 (NFκ-B2), which regulates cell proliferation, anti-apoptosis and cytokine secretion in many cancers." (PMID 24481412, 2014). "The NF-κB family (RelA (p65), c-Rel, RelB, p50/105 and p52/100) has been at the forefront of cancer research." (PMID 25184276, 2014). "NF-κB is a family of transcription factors composed of five members, the most important of which in cancer is the p65 (RelA) and p50 heterodimer." (PMID 25153725, 2014). "In the case of cancer-associated small indels, the statistically most significant results were with complexes related to RELA gene—NFKB1-RELA and RELA-REL complexes both had p value 7.56E-4." (PMID 25496518, 2014). "To-date, anti-NF-κB cancer therapy strategies have focused on targeting the canonical RelA pathway through IKKβ inhibition, with limited efficacy." (PMID 23451236, 2013). "The NF-κB family, which consists of p65 (RelA), RelB, p50/105 (NF-κB1), c-Rel, and p52/p100 (NF-κB2), are constitutively activated in many cancers." (PMID 23383209, 2013). "In our study, using both human cancer specimens and cell lines, clearly shows that NF-κB/relA activity significantly contributes to the metastasis of SCCHN." (PMID 20716363, 2010). "With the exception of c-Rel, each subunit was detected in the nucleus of cancer cells: significant nuclear expression of RelB, RelA, p52, and p50 was seen in 26.6, 15.6, 10.7, and 10.5% of cores, respectively." (PMID 16205698, 2005). "We also examined if there was a correlation between tumor stage and staining intensity or nuclear localization of p65/RELA in carcinomas." (PMID 16332260, 2005). "However, RelA also promotes the expression of pro-inflammatory genes in the context of other cancer types." (PMID 40982347, 2025). "Notably, TNF-α-induced phosphorylation of RelA at serine 276 in certain cancer cells facilitates the recruitment of DNA methyltransferase 1 (Dnmt1) to tumor suppressor genes (e.g., BRMS1)." (PMID 40562870, 2025). "This was in accordance with data from patients with RELA haploinsufficiency, in which no increased susceptibility to infections or cancer was reported." (PMID 38504985, 2024). "Furthermore, GSEA GO analysis of these overlapped RELA and RELB binding genes identified the top enriched terms as associated with metastasis, proliferation, stemness, and cancer relapse." (PMID 39418101, 2024). "Moreover, RelA-mediated glycolytic gene expression can augment the well-known Warburg effect in cancer cells." (PMID 38257735, 2023).